CDKN2A (cyclin dependent kinase inhibitor 2A)
Diseases named in the same sentence as CDKN2A in open-access papers (continued):
Sharing a sentence is not in itself a finding about the gene and the disease.
tumor (continued). "The presence of CDKN2A mutations correlates with adverse clinical outcomes, such as increased tumor size and invasion depth, which are significant predictors of poor survival in cSCC patients." (PMID 39925808, 2025). "CDKN2A encodes the tumor suppressor protein p16, which, when mutated, leads to unchecked cell cycle progression and has been associated with early tumor progression and poor clinical outcomes in PDAC." (PMID 41187942, 2025). "The tumour suppressor gene Cdkn2a,80 DNA damage repair gene Ddit4,81 oncogene Myc,82 and metabolism‐associated gene Pkm83 exhibited markedly heightened expression levels in these tumour cells." (PMID 40887856, 2025). "Despite being an EAC driver, the early loss of CDKN2A has a tumor-suppressive role supported by its higher occurrence in NP-BE than P-BE and EAC." (PMID 39753721, 2025). "The downregulation of CDKN2A mirrors the behavior observed in HCCs, where the loss of cell cycle control facilitates unchecked tumor growth." (PMID 40431665, 2025). "Further genetic alterations, notably in CDKN2A, were frequent and linked to poor prognosis, highlighting the complexity of tumor drug resistance in STAD." (PMID 40410601, 2025). "Hyper‐arrangement and CDKN2A (cyclin‐dependent kinase inhibitor 2A) deletion are associated with increased proliferation of tumor cells, reflecting active tumor growth and suggesting poor patient outcomes." (PMID 40264576, 2025). "While promoter hypermethylation is the most common epigenetic cause, aberrant methylation of CDKN2A exon 2 has also been associated with various tumor types." (PMID 40649906, 2025). "CDKN2A/B co‐mutations were significantly represented in tumours with STK11 (63%, 10/16, p = 0.024), KEAP1 (59%, 10/17, p = 0.045), and SPEN (90%, 9/10, p < 0.001) alterations, and in all tumours with MTAP alterations (100%, 16/16, p < 0.001)." (PMID 41015991, 2025). "More than 20% of familial CM cases are caused by a mutation in a high‐risk tumor predisposition gene, namely cyclin‐dependent kinase inhibitor 2A (CDKN2A)." (PMID 39609109, 2025). "CDKN2A/B: CDKN2A/B are tumor suppressor genes and their loss of expression contributes to malignant tumor progression by disrupting cell cycle regulation and enhancing cell proliferation." (PMID 40949165, 2025). "This was made feasible by using in vivo Crispr/Cas9-mediated gene editing to mutate the Cdkn2a TS locus at the time of tumor initiation." (PMID 41008846, 2025). "The MC3Ri tumor consisted primarily of the red subclone, which acquired CDKN2A and ETS1 mutations from the founding clone, possibly correlating with the emergence of the SHM2 clonotype." (PMID 40876452, 2025). "Early tumor evolution is marked by CDKN2A/B loss and EGFR, platelet-derived growth factor receptor A (PDGFRA), and CDK4 gains." (PMID 40565099, 2025). "Most tumours with previously identified RB1 defects were associated with very high CDKN2A transcript levels as expected, which were also observed in some tumours with very low RB1 transcript levels." (PMID 36453028, 2024). "The methylation status of CDKN2A is associated with tumor progression and has been correlated with decreased survival in CRC patients, indicating its potential as a prognostic biomarker." (PMID 39370455, 2024). "Differential expression between normal tissues and BRCA tissues at each tumor stage was found in almost all cuproptosis-associated genes; however, only LIPT1, DLAT, PDHA1, and CDKN2A were differentially expressed among tumor stages." (PMID 39432636, 2024).
tumor (continued). "This signature, in addition to a smoking signature, CDKN2A/B loss, patient smoking status, and a tumor latency of <10 years represent a key set of molecular and clinical variables that characterize a tumor with poor prognosis following RT." (PMID 39113632, 2024). "The protein product of the CDKN2A gene, p16, plays a critical role in cell cycle regulation via its interaction with the retinoblastoma tumor suppressor encoded by the RB1 gene." (PMID 39684714, 2024). "CDKN2A is a tumor suppressor gene that encodes the p16INK4a protein and serves as an inhibitor of cell cycle progression." (PMID 39108689, 2024). "Many epigenetic alterations favored in variant cultures, including hypermethylation of the CDKN2A promoter, have also been observed during human tumor progression." (PMID 39399685, 2024). "For the associations of CDKN2A mutations in tumor and blood samples with survival, only high CDKN2A mutation abundance in ctDNA was linked to inferior PFS (P < 0.001)." (PMID 38378604, 2024). "When it comes to group Mix vs. Pro-Meta, CDKN2A (Cyclin Dependent Kinase Inhibitor 2 A) seems specifically mutated in the Mix group and is known to be an important tumor suppressor gene, indicating a disordered cell cycle in this group." (PMID 38824541, 2024). "Poor prognostic factors in the RT cohort include a short tumor latency, smoking status, the presence of the smoking and X-ray therapy mutational signatures, and CDKN2A copy number loss." (PMID 39113632, 2024). "This suggests that the microenvironment of the CDKN2A+ region is predisposed to immune suppression, angiogenesis, and tumor invasion." (PMID 38888512, 2024). "p16 (INK4a) (cyclin-dependent kinase inhibitor 2A (CDKN2A)) is a tumor-suppressor protein associated with cell cycle progression, specifically regulating the transition from the G1 phase to the S phase." (PMID 39727978, 2024). "p16 is a tumor suppressor encoded by the CDKN2A gene whose expression is lost in approximately 50% of all human cancers." (PMID 38626341, 2024). "The homozygous loss of tumor suppressors CDKN2A/B in our case highlights the importance of this gene in the tumorigenesis and aggressiveness." (PMID 37951844, 2024). "Tumour specific variants in CDKN2A, NOTCH1 and KMT2D present at baseline were detected longitudinally in ctDNA and increased in frequency at recurrence." (PMID 38846976, 2024). "Clinicogenomic analysis of radiation-associated bladder cancer uncovered mutational signatures that, in addition to a short tumor latency, smoking, and CDKN2A loss, are associated with a poor outcome." (PMID 39113632, 2024). "The deletion of chromosome 9 is linked to the loss of important genes CDKN2B, p14, and CDKN2A, which normally suppress tumor development." (PMID 39022728, 2024). "CDKN2A, responsible for encoding a crucial cell-cycle regulator, prominently emerges as the most frequently altered tumor suppressor gene." (PMID 38395786, 2024). "Proteins linked to cancers (e.g., the tumour suppressor, CDKN2A), CNS disorders (e.g., the myelin constituent, PMP22), and developmental disorders (e.g., skeleton and tooth development protein, SLC10A7) were represented at fCEAA and fEAA extremes." (PMID 39401228, 2024). "Theoretically, the increase of metastatic tumor sites and neoantigens caused by CDKN2A ALT provides an opportunity for the tumor-infiltrating white blood cells (TILs) to recognize and attack cancer cells in the tumor tissues." (PMID 38822443, 2024). "Chromosome 9p21.3 loss eliminates CDKN2A/B tumor suppressors and often encompasses codeletions of a cluster of 16 type I IFN genes." (PMID 38856716, 2024). "In patient TFCP2-HD-5, CDKN2A deletions were present at both time points, 32 months apart, but additional mutations occurred in the advanced tumor." (PMID 38168093, 2024).
tumor (continued). "In particular, high CDKN2A expression is linked to activated immune cells, indicating its role in tumor immunity and its potential as a prognostic biomarker and therapeutic target." (PMID 38666907, 2024). "The retrospective analysis of the initial tumor identified a BRAF V600E mutation associated with CDKN2A deletion." (PMID 39399174, 2024). "Somatic mutations in CDKN2A, which encodes the cell-cycle inhibitor p16, have been observed in numerous cancers, establishing its role as a tumor suppressor." (PMID 39734333, 2024). "Tumor regions expressing CDKN2A exhibit distinctive SPP1+ tumor-associated macrophage (TAM) infiltration and MMP7 enrichment, along with unique signaling crosstalk with adjacent areas." (PMID 38888512, 2024). "The aim of this study was to examine the concentration of CDKN2A and Ki-67 proteins in 54 tumor and margin samples of HNSCC and to evaluate their association with the clinical and demographic variables." (PMID 39590385, 2024). "Methylation of CDKN2A promoter was associated with lymph node metastases and large tumor size in primary colorectal cancer tissues." (PMID 38561743, 2024). "The TME provides a new perspective for understanding the comprehensive mechanisms underlying how CDKN2A promotes tumor progression and resistance to cuproptosis." (PMID 38888512, 2024). "For example, recurrent amplification of oncogenes such as MYC, ERBB2 (HER2), and FGFR1, and significant loss of tumor suppressors such as CDKN2A and CDKN2B were observed in the high-CRRS group." (PMID 36936912, 2023). "CDK1 inhibition has been shown to selectively inhibit tumor growth in GC cells with CDKN2A mutations and in GC mice models with CDKN2A mutations." (PMID 38069284, 2023). "In accordance with previous reports, gene deletion and/or copy number loss events of CDKN2A were identified in several cases; they were also observed in Early-Ad stages, although the disruption of tumor-suppressor genes rarely occur at these stages." (PMID 38102134, 2023). "CDKN2A is one of the most reported tumor suppressors in cancer progression and associated with immune evasion by T cell killing." (PMID 36961395, 2023). "To elucidate the molecular mechanisms underlying the frequent mutation of Cdkn2a in the early stage of DSS tumor development, we focused on changes in Cdkn2a expression, which is a marker for senescence signaling." (PMID 37845228, 2023). "Only 50% of cases with homozygous CDKN2A deletions (14/28) had complete loss of p16 immunoreactivity (“0” score), while 28% (A/B) had minimal staining (“+1” score, 0–9% positive tumor cells)." (PMID 37093270, 2023). "CDKN2A was downregulated in the tumors with a high tumor mutation load compared to the tumors with two or fewer mutations." (PMID 38188288, 2023). "Analysis of these data above revealed a potential association between CDKN2A expression and immune activation in the tumor microenvironment (TME)." (PMID 36961395, 2023). "iCluster1 tumours exhibited features such as higher tumour grade and presence of macrovascular invasion, a low frequency of CDKN2A silencing and CTNNB1 gene and TERT promoter mutations compared to iCuster2 and iCluster3." (PMID 36707636, 2023). "The expression of MYCN and CDKN2A was associated with tumor stage, metastasis, and overall survival in our cohort." (PMID 37878133, 2023). "Co-mutations in the tumor suppressors CDKN2A and KEAP1 occur more commonly in patients with KRASG12C-mutated tumors showing intrinsic resistance to adagrasib and/or sotorasib." (PMID 38106234, 2023). "We have previously demonstrated in contrast with LPS stimulation, which induces Il1b expression in both BMDM and MG cultures, organotypic tumor slices generated by Cdkn2a loss and PDGFB overexpression only induce Il1b expression in BMDM cocultures." (PMID 37733448, 2023).
tumor (continued). "Homozygous deletion of the CDKN2A/B locus has been implicated in both gliomagenesis and tumor progression through dysregulated cell proliferation." (PMID 37138345, 2023). "In fact, CDKN2A (encoding p16INK4A) exerts a far-reaching tumor-inhibition purpose by enhancing the KRAS signaling pathways activity in accelerating the malignant progression of cancer." (PMID 37390335, 2023). "CDKN2A, a tumor suppressor gene, encodes the p16INK4a protein that negatively regulates the cell cycle, which is an important tumor suppressor protein." (PMID 36911392, 2023). "Deletion, point mutation, and/or promoter methylation can cause damage to CDKN2A gene function, which, in turn, can lead to uncontrolled cell proliferation, giving rise to the evolution and progression of the tumor." (PMID 36961395, 2023). "CDKN2A has been identified as a tumour suppressor associated with the detection of regulatory gene hubs." (PMID 37697330, 2023). "The concurrent biallelic loss of CDKN2A next to heterozygous MTAP gene deletion probably reflects genetic tumor progression and characterizes the spatial heterogeneity of PM." (PMID 37894345, 2023). "We carried out gene set enrichment analysis (GSEA) of hallmark gene sets in different tumor types to find out the CDKN2A associated cancer characteristics." (PMID 36961395, 2023). "Among them, CDKN2A encodes a nucleolar protein involved in triggering cell cycle arrest and apoptosis to suppress tumor growth." (PMID 37352167, 2023). "We found that the expression of CDKN2A was significantly associated with tumor immune-related pathways such as the TNFα signaling pathway via NFκB, IFN-α response, IFN-γ response, allograft rejection pathway, and inflammatory response." (PMID 36961395, 2023). "Mutations or changes in the CDKN2A gene can lead to an impaired ability to suppress tumor growth, which can increase the risk of cancer." (PMID 37504268, 2023). "As a tumor suppressor gene, CDKN2A encodes the p16 protein, which can inhibit the cell cycle, and up-regulation of CDKN2A can promote tumor proliferation." (PMID 38078880, 2023). "The cyclin-dependent kinase inhibitor 2A (CDKN2A) gene’s homozygous deletion encodes the p16NK4a and p14ARF tumor suppressors, which are more frequently observed in both primary and secondary GBM." (PMID 38201528, 2023). "The prevalence of homozygous CDKN2A/B deletions in the included studies was 0.049 (95% CI 0.040–0.057), with higher tumor grades associated with a significantly greater proportion of CDKN2A/B deletions." (PMID 38017560, 2023). "This revealed that loss of Cdkn2a caused reduced latency to tumour development and increased Ki67+ fraction, while maintaining the EHE specific transcriptome." (PMID 37296967, 2023). "Low amounts of tumor-stromal collagen were associated with poor differentiation (multivariable OR = 3.82, 95%CI = 1.41–12.2, P = 0.008) and CDKN2A/p16 alteration (OR [95%CI] = 2.06 [1.08–4.02], P = 0.03)." (PMID 37477731, 2023). "While MLL3 likely regulates a plethora of genes that contribute to its tumor-suppressive potential, the well-defined and potent antitumor functions of Cdkn2a-encoded proteins make them attractive candidates as functionally relevant MLL3 effectors." (PMID 37261974, 2023).
tumor (continued). "Non-A-on label biomarkers (A-off label, B-on label and B-off label) showed a modest and tumour-type-dependent metastatic increase, which was mainly linked to the increased alteration frequency of KRAS exon 2 mutations and CDKN2A loss in advanced tumour stages." (PMID 37165194, 2023). "Whilst the tumor suppressor’s p14ARF and p16INK4A are proven to be encoded by CDKN2A, the p15INK4B protein is encoded using CDKN2B." (PMID 37845622, 2023). "We have revealed an intriguing connection between PDACs with low tumor-stromal collagen and the variant allele frequency of CDKN2A/p16." (PMID 37477731, 2023). "Recently, CDKN2A as a negative regulator of cuproptosis, has been found to be associated with tumor prognosis and identified as a potential chemotherapy response predictor." (PMID 37784106, 2023). "The loss of p16, mostly related to a CDKN2A deletion, abrogates the senescent features of tumor cells stably overexpressing altered BRAF." (PMID 36831610, 2023). "For example, CDKN2A (encoding for p21) is a known cancer driver, frequently altered at early stages of tumor development." (PMID 37864038, 2023). "We performed gene set enrichment analysis of the hallmark gene sets from different tumor types to identify CDKN2A-associated cancer features." (PMID 36961395, 2023). "Homozygous deletion of CDKN2A determined by FISH is formally considered to be diagnostic of malignancy if more than 20% of the tumor nuclei show loss of both 9p21 signals." (PMID 37894345, 2023). "Mucinous carcinomas are uncommon tumours associated with copy-number loss of CDKN2A and KRAS alterations." (PMID 37091785, 2023). "Consistent with known genomic hallmark of PXA, the loss in short arm of the chromosome 9 associated with homozygous 9p21.3 deletion involving CDKN2A/B locus was identified in both the original patient’s tumor and the PDX sample." (PMID 37280243, 2023). "In the present study, CDKN2A had the highest frequency (35% of cases) of tumor-shared pathogenic variants, with all being stop-gain (p.R80X, p.R58X, and p.W110X)." (PMID 35884575, 2022). "Retrospective analysis of clinical data in different tumor types revealed an association of CDKN2A loss with worse overall and progression-free survival following ICI treatment in combination with chemotherapy." (PMID 35273962, 2022). "CDKN2A encodes the protein p14ARF, a tumor suppressor that was reported to sequester HIF-1α in the nucleolus and thereby inhibit HIF-1-mediated transcription." (PMID 36480544, 2022). "As CDKN2A increases tumor cell proliferation, loss of this tumor suppressor gene increases proliferation and invasiveness." (PMID 36380219, 2022). "A study reported that 11% of LGG differed in CDKN2A deletion status in the primary vs the relapse tumour, and that acquisition of the deletion was associated with worse prognosis." (PMID 35842717, 2022). "This is consistent with recently published data indicating the loss of 9p21—encompassing CDKN2A/B—confers a cold tumor immune microenvironment and resistance to ICI." (PMID 36536472, 2022). "An additional adenocarcinoma with homozygous deletion of CDKN2A showed loss of mTAP expression in a subset of the tumor." (PMID 35565429, 2022). "The progression of PDAC occurs due to the loss of the tumor-suppressor gene cyclin-dependent kinase inhibitor 2A (CDKN2A)." (PMID 35409064, 2022). "CDKN2A/2B loss or mutation are associated with tumor progression, invasion and metastasis and have been reported in 7–18% of iCCAs22–24." (PMID 36335135, 2022). "As expected, CNV detection was muted in urine samples compared to pure tumor; this was particularly apparent in the low rate of copy number loss events observed in urine (such as CDKN2A) compared to that in the literature." (PMID 36233691, 2022).